MBD4 (methyl-CpG binding domain 4, DNA glycosylase)
Description:
Mismatch-specific DNA N-glycosylase involved in DNA repair. Has thymine glycosylase activity and is specific for G:T mismatches within methylated and unmethylated CpG sites. Can also remove uracil or 5-fluorouracil in G:U mismatches. Has no lyase activity. Was first identified as methyl-CpG-binding protein.
Synonyms: MED1; TPDS2; UVM1
Tractability: PROTAC: ubiquitination databases record sites on it; its protein half-life has been measured.
Target class: Enzyme; Hydrolase
Gene: Protein-coding gene on chromosome 3 (129,430,947 to 129,440,543, reverse strand). Ensembl gene ENSG00000129071.
Subcellular location: Nucleus
Subcellular location (Human Protein Atlas): Nuclear speckles
Pathways (Reactome):
DNA Repair: Cleavage of the damaged pyrimidine; Displacement of DNA glycosylase by APEX1; Recognition and association of DNA glycosylase with site containing an affected pyrimidine
Gene Ontology:
Molecular function: protein binding; pyrimidine-specific mismatch base pair DNA N-glycosylase activity; DNA binding; DNA endonuclease activity; DNA N-glycosylase activity; satellite DNA binding; catalytic activity
Biological process: depyrimidination; DNA repair; DNA damage response; response to estradiol
Cellular component: nuclear speck; nucleoplasm; nucleus
Genetic constraint (gnomAD): Loss-of-function variants: 46 observed, 57.49 expected, observed/expected ratio (o/e) 0.8, 90% interval 0.63 to 1.02. The upper end of that interval is the gene's LOEUF score, 1.02, which puts it in group 4 of 6, group 1 being the genes least tolerant of losing a copy. Missense variants: 599 observed, 682.26 expected, observed/expected ratio (o/e) 0.88, 90% interval 0.82 to 0.94. Synonymous variants: 225 observed, 232.84 expected, observed/expected ratio (o/e) 0.97, 90% interval 0.87 to 1.08.
Gene-disease validity (ClinGen):
ClinGen rates the evidence that MBD4 causes each of these diseases.
tumor predisposition syndrome 2 (autosomal recessive): Moderate. An autosomal recessive cancer predisposition syndrome characterized by the onset of various types of tumors or malignancies in young adulthood.
uveal melanoma (autosomal dominant): Moderate. A melanoma derived from melanocytes of the uveal tract.
Homologues: Orthologues: chimpanzee MBD4 (99% identical), macaque MBD4 (93% identical), dog MBD4 (77% identical), pig MBD4 (76% identical), rabbit MBD4 (71% identical), mouse Mbd4 (66% identical), rat Mbd4 (66% identical), tropical clawed frog mbd4 (36% identical).
Diseases named in the same sentence as MBD4 in open-access papers:
MBD4 is named in the same sentence as 75 diseases in open-access papers, as found by Europe PMC text mining. Sharing a sentence is not in itself a finding about the gene and the disease. The quoted sentences say what the papers report.
colorectal cancer (11 papers, 2000 to 2025). A primary or metastatic malignant neoplasm that affects the colon or rectum. "Inherited defects in the base-excision repair gene MBD4 predispose individuals to adenomatous polyposis and colorectal cancer Which is characterized by an accumulation of C > T transitions resulting from spontaneous deamination of 5’-methylcytosine." (PMID 37957685, 2023). "Like Mbd3, other Mbd proteins, especially Mbd2 and Mbd4, are associated with progression of cancer such as colorectal cancer, albeit by different mechanisms." (PMID 28467410, 2017). "The MBD4 Glu346Lys polymorphism is associated with increased risk of colorectal cancer, esophageal squamous cell carcinoma, and lung adenocarcinoma." (PMID 27086921, 2016). "Such tumors are probably rare, with mainly UMs, acute myeloid leukemias, colorectal carcinomas, and gliomas, but this list might be underestimated since the precise spectrum of MBD4-associated diseases remains to be defined." (PMID 36323843, 2022). "A high prevalence in colorectal cancer patients is noteworthy considering the recent addition of colorectal adenomas to the tumour spectrum of individuals with very rare biallelic loss-of-function germline variants in MBD4 and a somatic CpG hypermutation phenotype." (PMID 39026103, 2024). "Deleterious germline MBD4 variants cause recessive tumor predisposition syndrome 2 (TPDS2; OMIM 619975), linked especially to acute myeloid leukemia, colorectal cancer, and UM." (PMID 39344744, 2025). "MBD4 has been observed to be epigenetically downregulated in colorectal and ovarian cancer, and low MBD4 expression significantly predicts reduced survival in colorectal cancer." (PMID 27086921, 2016). "Furthermore, Western analysis of nuclear proteins of HCT116 (heterozygous wt/mut) and HCA7 (homo- or hemi-zygous mutant) colorectal carcinoma cell lines with H-300 antibody detected both forms of MBD4." (PMID 17285135, 2007). "In fact, overexpression of a truncated form of MBD4 lacking the glycosylase domain in a BigBlue-transfected human MSH6-deficient colorectal cancer cell line, led to a 2-fold increase in mutation frequency and predisposed to chromosomal instability, compared to controls." (PMID 26503472, 2015).
uveal melanoma (11 papers, 2018 to 2025). "While UV-mediated cutaneous melanoma is associated with a C > T mutagenesis signature distinct from CpG hypermutations, a small subset of the more rare uveal melanoma (UM) is associated with MBD4-associated CpG hypermutations (Fig. EV2)." (PMID 39026103, 2024). "A recent case study reported an exceptional response to ICI in a patient with uveal melanoma, biallelic loss of MBD4, and a somatic CpG hypermutation." (PMID 39026103, 2024). "In contrast to findings with uveal melanoma where heterozygotes for MBD4 LOF variants appear to be at a 4- to 20-fold increased risk, our limited data show no convincing evidence for a comparable effect on the relative risk of developing polyposis and/or CRC." (PMID 35460607, 2022). "Perhaps most significantly, the presence of germline MBD4 mutations in uveal melanoma reintroduced the clinical significance of mutational burden in the dawning era of immunotherapy." (PMID 36618446, 2021). "MBD4 is involved in base excision repair, and those responding uveal melanomas are characterized by a high mutational burden." (PMID 33276788, 2020). "Additionally, MBD4 deficiency has been identified as a predictive marker for response to immune checkpoint inhibitors in uveal melanoma." (PMID 40320296, 2025). "Heterozygous germline MBD4 PVs are associated with genetic predisposition to uveal melanoma." (PMID 40237887, 2025). "Recently, there have been reports of a new germline mutation associated with uveal melanoma, which may also be responsible for the development of additional malignancies, namely the mutation of the MBD4 gene (responsible for repairing DNA damage)." (PMID 38087265, 2023). "A high mutational burden is associated with a good prognosis in CRC, and we speculate that MANS CRCs may respond to immune checkpoint inhibitors, as has been reported in MBD4-deficient uveal melanomas." (PMID 35460607, 2022). "We further confirm the exquisite activity of gemcitabine in an MBD4-deficient co-clinical model as (i) it completely prevented the development of an MBD4-deficient uveal melanoma patient-derived xenograft and (ii) treatment in the corresponding patient resulted in an exceptional tumor response." (PMID 36323843, 2022). "In addition to two independent reports demonstrating significant “outlier” responses of uveal melanoma to pembrolizumab in the setting of germline MBD4 mutations, the direct mechanism of pathogenesis also has begun to be uncovered." (PMID 36618446, 2021). "Here, the authors describe a new hypermutated phenotype due to germline mutations and subsequent somatic loss of heterozygosity of MBD4, and a dramatic response to the PD-1 inhibitor pembrolizumab in a patient with a MBD4-inactivated hypermutated uveal melanoma." (PMID 29760383, 2018). "Here we present a metastatic uveal melanoma patient with an exceptional high sensitivity to a PD-1 inhibitor associated with outlier CpG>TpG mutation burden, MBD4 germline deleterious mutation, and somatic MBD4 inactivation in the tumor." (PMID 29760383, 2018). "Indeed, a recent comprehensive analysis of MBD4 mutations in uveal melanoma confirmed the role of MBD4 as a tumor suppressor in line with Knudson's two‐hit hypothesis, and convincingly joined BAP1 as the only identified predisposing genes for uveal melanoma." (PMID 36618446, 2021). "A striking example is patients with uveal melanoma another type of melanoma, that is resistant to all immunotherapy regimens, however, a subset of patients, harboring inactivating mutations in methyl-CpG-binding domain protein 4 (MBD4) exhibit sensitivity to ICT." (PMID 33276788, 2020). "In the short term, genetic testing for MANS could be implemented readily by incorporating MBD4 into existing gene panels used in diagnostic testing for adenomatous polyposis, CRC, early-onset AML, and uveal melanoma." (PMID 35460607, 2022).
uveal melanoma (continued). "We treated isogenic HAP1-KO MBD4 and HAP1-WT cell lines with camptothecin, doxorubicin, gemcitabine, cytarabine, paclitaxel, and dacarbazine, an alkylating agent commonly used to treat uveal melanoma patients (together with its active form, MTIC)." (PMID 36323843, 2022).
acute myeloid leukemia (8 papers, 2019 to 2025). Acute myeloid leukemia (AML) is a group of neoplasms arising from precursor cells committed to the myeloid cell-line differentiation. "Both MDS and acute myeloid leukemia have been observed in humans with biallelic mutation of MBD4." (PMID 37984997, 2023). "Loss of MBD4 expression due to germline mutations was detected in a small number of acute myeloid leukemia (AML) patients." (PMID 32547565, 2020). "A recent study has shown that germline mutation of MBD4 increases the susceptibility to develop acute myeloid leukemia (AML)." (PMID 31245293, 2019).
colon cancer (7 papers, 2007 to 2024). "In agreement with this, Mbd4−/− mice exhibit a marked increase in C to T mutations at CpG sites and higher occurrence of these mutations has been demonstrated in colon tumors in crosses of Mbd4−/− mice with ApcMin mice." (PMID 37957685, 2023). "Here we show that Mbd4 suppresses morbidity and mortality in a mouse model of UC inflammation-associated colon cancer." (PMID 27086921, 2016). "For example, the methyl-CpG binding domain protein, MBD4, which is involved in mismatch repair at CpG sites, is affected by frameshift mutations in over 40% of microsatellite unstable sporadic colon cancers." (PMID 23049694, 2012). "The mutation occurs in 20–43% of cases (mixed tissue samples), whereas microdissected samples (enriched for tumour cells) of 89% sporadic MSI colon tumours had truncated MBD4 mutations in at least one focus tested." (PMID 17285135, 2007). "In this study, we describe how truncated MBD4 can inhibit normal glycosylase activity in a cell-free system, and increase mutation frequency across a wide spectrum of mutation changes in living colon cancer cells even on a background of pre-existing MSI." (PMID 17285135, 2007). "In conclusion, we demonstrated that FTD is effective to 5-FU-refractory colon cancer cell independently of the DNA MMR status, and that MBD4 frameshift mutation caused by DNA MMR deficiency enhance FTD sensitivity through G2/M arrest." (PMID 29545913, 2018). "An MBD4 frameshift mutation resulting in a premature stop codon and truncated protein is frequently found in colon tumors; this truncated version of MBD4 impairs DNA repair in a dominant negative fashion." (PMID 27086921, 2016). "Here, we report that the Mbd4 DNA glycosylase is protective in the azoxymethane/dextran sodium sulfate (AOM/DSS) mouse model of inflammation-driven colon cancer." (PMID 27086921, 2016). "To investigate the role of Mbd4 in inflammation-driven colon cancer, we compared the effects of AOM/DSS treatment on Mbd4−/− versus WT mice." (PMID 27086921, 2016). "We used mouse CMT93 cells, a colon cancer cell line that has prominent heterochromatin sites as evidenced by DAPI staining, to test our hypothesis that MBD4 and UHRF1 might associate with each other at heterochromatin sites." (PMID 25358258, 2015). "However, in humans, frameshift mutation of MBD4, rather than deletion, is what occurs in up to 43% of microsatellite unstable colon cancers." (PMID 17285135, 2007).
autoimmune disease (4 papers, 2017 to 2023). A disorder resulting from loss of function or tissue destruction of an organ or multiple organs, arising from humoral or cellular immune responses of the individual to their own tissue constituents. "There are some indications that MBD4 is involved in the pathogenesis of autoimmune diseases by provoking DNA demethylation of costimulatory genes that may lead to aberrant immune activation." (PMID 32547565, 2020). "Altered expression of MBD4 has also been observed in several autoimmune disorders; however, the role of MBD4 in the pathogenesis of autoimmune diseases remains unclear." (PMID 29018507, 2017). "MBD4 expression is decreased in systemic autoimmune diseases, such as SLE and SSC, but is increased in organic autoimmune diseases, such as ITP and vitiligo." (PMID 29018507, 2017). "The increased expression of MBD2 and MBD4 in the AAA group was also consistent with the increased rate of DNA methylation, further enhancing the main function of regulatory T cells to inhibit autoimmune diseases." (PMID 31001930, 2019). "However, a direct role for MBD4 in B cells of (autoantibody-mediated) autoimmune diseases has not been reported." (PMID 32547565, 2020). "Therefore, the abnormal disease-specific expression level of MBD4 in SLE CD4+ T cells may have unique effects on immune activation, which causes deterioration into a systemic disease in SLE rather than an organ-specific autoimmune disease." (PMID 29018507, 2017). "One reason for the difference of MBD4 expression among these autoimmune diseases may be that the SLE is a systemic disease, not an organ-specific autoimmune disease, such as vitiligo." (PMID 29018507, 2017).
polyposis (4 papers, 2022 to 2025). "The limited data suggests that constitutional monoallelic inactivation of MBD4 does not increase the risk of CRC and/or polyposis." (PMID 40237887, 2025). "We cannot rule out the possibility that individuals heterozygous for an MBD4 LOF variant have a small increased risk of CRC and/or polyposis, but at present, no colonoscopy surveillance beyond population screening or local guidelines based on familial history for CRC is recommended." (PMID 35460607, 2022).
systemic sclerosis (4 papers, 2017 to 2025). A chronic disorder, possibly autoimmune, marked by excessive production of collagen which results in hardening and thickening of body tissues. "In SSc (systemic sclerosis), the expression of other MBD family molecules, such as the mRNA of MBD3 and MBD4, is reduced compared to controls, and a positive correlation exists between the relative levels of MBD4 and DNA methylation in the SSc group." (PMID 40533455, 2025). "Abnormal expression of MBD4 has been reported in several other diseases, for example, SLE, systemic sclerosis (SSC), primary immune thrombocytopenia (ITP), and vitiligo." (PMID 29018507, 2017).
adenomatous colorectal polyposis (3 papers, 2022 to 2025). "In addition to FAP and MUTYH-associated polyposis, colorectal adenomatous polyposis can be caused by other hereditary diseases, including polymerase proofreading-associated polyposis, NTLH1 tumor syndrome, and MBD4-associated neoplasia syndrome." (PMID 38647838, 2024).
colorectal polyposis (3 papers, 2022 to 2026). "Here, by applying whole-genome and whole-exome sequencing (WGS and WES), we identified loss-of-protein-function (LOF) variants of the BER gene MBD4 as the cause of an autosomal recessive syndrome of colorectal polyposis and extracolonic neoplasia." (PMID 35460607, 2022). "Incorporation of MBD4 into diagnostic gene panels for colorectal polyposis, AML, and uveal melanoma at one of our centers has led to the identification of a further individual (DB1-70) with MBD4-associated neoplasia syndrome (MANS)." (PMID 35460607, 2022). "Two of three individuals with AML previously identified to have MBD4 deficiency were noted to have colorectal polyps, without information on their type or multiplicity." (PMID 35460607, 2022). "We also confirmed that no replication strand bias existed in a set of MBD4-mutant colorectal polyps, consistent with the very large number of CpG > TpG changes in those tumours being independent of DNA replication." (PMID 40855317, 2025).
colorectal tumors (3 papers, 2008 to 2022). "MBD4-deficient polyps harbored somatic mutations in similar driver genes to sporadic colorectal tumors, although AMER1 mutations were more common and KRAS mutations less frequent." (PMID 35460607, 2022). "The correlation between MBD4 deficiency and intestinal tumorigenesis has also been assessed in humans, in which 26–43% of microsatellite unstable colorectal tumours show mutations in the MBD4 gene." (PMID 18542062, 2008). "The DNA glycosylase gene MBD4 safeguards genomic stability at CpG sites and is frequently mutated at coding poly-A tracks in mismatch repair (MMR)-defective colorectal tumors (CRC)." (PMID 26503472, 2015).
glioma (3 papers, 2022 to 2024). A benign or malignant brain and spinal cord tumor that arises from glial cells (astrocytes, oligodendrocytes, ependymal cells). "Previous studies described CpG hypermutation in MBD4-deficient early-onset AML, and our study further expands it to paediatric ALL and paediatric-type diffuse high-grade gliomas." (PMID 39026103, 2024).
intestinal tumor (3 papers, 2008 to 2024). "Moreover, MBD4−/− mice with a Apc(Min/+) background develop more intestinal tumours than Apc(Min/+) MBD4+/+ mice." (PMID 18542062, 2008).
lupus (3 papers, 2013 to 2017). "Other investigators described significantly higher mRNA levels of other enzymes (MBD1, MBD3, and MBD4), involved in the DNA methylation process, in patients with lupus." (PMID 28349196, 2017). "In addition, we observed an obvious negative correlation between the MBD4 mRNA expression levels and the Systemic Lupus Erythematosus Disease Activity Index (SLEDAI) scores." (PMID 29018507, 2017).
ovarian carcinoma (3 papers, 2015 to 2023). A malignant neoplasm originating from the surface ovarian epithelium. "On the other hand, alternative mechanisms of biallelic MBD4 inactivation have been described: in CRC frameshift mutations were accompanied by loss of heterozygosity (LOH) of the wild type allele; and silencing of MBD4 by promoter hypermethylation can occur in CRC and ovarian cancer." (PMID 26503472, 2015).
breast carcinoma (2 papers, 2015 to 2018). "In summary, findings presented here show that reduced RNF144A expression in breast cancer cells is regulated by promoter hypermethylation and MBD4 in breast cancer cells." (PMID 29473320, 2018). "Evidence from pharmacological and genetic modulation of MBD4 demonstrated that MBD4 is involved in RNF144A expression in breast cancer cells." (PMID 29473320, 2018). "More recently, it was reported that the RON receptor tyrosine kinase upregulates MBD4 through activation of the phosphoinositide 3‐kinase (PI3K) pathway to promote breast cancer metastasis." (PMID 29473320, 2018). "We next examined whether MBD4 is involved in the regulation of RNF144A in breast cancer cells." (PMID 29473320, 2018). "There is a marginal correlation between the expression levels of MBD4 and RNF144A in all of patients with breast cancer (n = 1093, p = 0.0738)." (PMID 29473320, 2018). "Following these observations, we next examined whether there is a negative correlation between the expression levels of MBD4 and RNF144A in breast cancer in The Cancer Genome Atlas (TCGA) database." (PMID 29473320, 2018).